TSC1 (TSC complex subunit 1)
Diseases named in the same sentence as TSC1 in open-access papers (continued):
Sharing a sentence is not in itself a finding about the gene and the disease.
vitiligo (1 paper, 2024). Generalized well circumscribed patches of leukoderma that are generally distributed over symmetric body locations and is due to autoimmune destruction of melanocytes. "The detection of this novel pathogenic TSC1 variant in the patient with atypical vitiligo‐like skin lesions enrolled in our study ultimately resulted in the diagnosis of TSC." (PMID 38439608, 2024).
von Hippel-Lindau disease (1 paper, 2020). An autosomal dominant disorder caused by pathogenic variants in the VHL gene, leading to an increased risk of various benign and malignant tumors, including hemangioblastomas, retinal hemangiomas, endolymphatic sac tumors, renal cell carcinoma, and pheochromocytomas. "Key syndromes include multiple endocrine neoplasia type 1 (MEN1), von Hippel–Lindau disease (VHL), neurofibromatosis type 1 (NF1), and tuberous sclerosis complex (TSC), which are characterized by germline mutations in the tumor-suppressor genes MEN1, VHL, NF1, and TSC1 or TSC2, respectively." (PMID 32850899, 2020).
tumor (392 papers, 2006 to 2026). "In the rare and aggressive Scirrhous-HCC subtype, which is characterized by dense fibrous stroma and small tumor nests, frequent Tuberous Sclerosis Complex 1 (TSC1)/Tuberous Sclerosis Complex 2 (TSC2) mutations have been prevalent." (PMID 41522204, 2026). "TSC2 is a tumor suppressor gene that encodes the protein Tuberin complexing with Hamartin, the protein encoded by TSC1, and together they inhibit the mammalian target of rapamycin (mTOR) pathway, which is crucial for cell growth, metabolism, and proliferation." (PMID 41522204, 2026). "Genetic studies suggest that it is associated with mutations in the tumor suppressor genes TSC1 or TSC2." (PMID 40989692, 2025). "The AMPECT trial evaluated the significant anti-tumor activity of nab-sirolimus in patients with advanced or metastatic malignant PEComa carrying mutations in the TSC1/TSC2 genes or activation of the mTOR pathway." (PMID 40989692, 2025). "An inactivating mutation in two tumor-suppressor genes—TSC1 and TSC2—is the cause of this syndrome, and TSC2 mutations make up 80–90% of all mutations." (PMID 39852149, 2025). "This study systematically evaluated the impact of TSC1 deficiency on tumor proliferation, immune microenvironment, and therapeutic responses." (PMID 41445741, 2025). "The deletion, rearrangement, or inactivating mutations of the tumor-suppressor genes TSC1 or TSC2 can lead to uncontrolled expression of the proteins hamartin and tuberin." (PMID 40283547, 2025). "In vivo experiments further confirmed that TSC1 knockdown significantly promoted tumor growth (with TSC1-deficient groups showing maximal tumor weight and volume), while anti-PD-1 monotherapy and rapamycin exhibited the most potent tumor-suppressive effects." (PMID 41445741, 2025). "In patients carrying patients carrying TSC1/2 mutations everolimus combined with pembrolizumab synergistically inhibits tumor growth and enhances immune response." (PMID 40989692, 2025). "As tumor suppressor genes, mutation and inactivation of TSC1/TSC2 enable cells to evade immune surveillance, promote tumor‐related protein expression, and contribute to tumorigenesis." (PMID 41383536, 2025). "Both enzymes have been implicated in tumor progression, and our findings confirm that their downregulation correlates with the immunosuppressive phenotype of TSC1-deficient CRC cells." (PMID 41445741, 2025). "The assessment of the cancer genome profile revealed the stability of microsatellite status, a tumor mutation burden of 4 mutations per megabase (Muts/Mb), alterations in TSC1 and APC, and amplification of ERBB4." (PMID 39846235, 2025). "An inactivating mutation in two tumor-suppressor genes—TSC1 and TSC2—is the cause of this syndrome, and TSC2 mutations made up 80–90% of all mutations." (PMID 39852149, 2025). "RNA-seq analysis revealed 127 differentially expressed genes that were shared among NF1-, TSC1-, or TβRII-deficient 4T1 tumor cells compared to the 4T1-C1 control." (PMID 38997291, 2024). "Tuberous sclerosis complex (TSC, OMIM: #191090), a severe autosomal dominant disorder, is caused by disease-causing variants in either of the tumor suppressor genes, TSC1 (OMIM: #605284) or TSC2 (OMIM: #191092)." (PMID 39187374, 2024). "They established the uniform presence of TSC1 mutation across all analyzed tumor samples, confirming its clonal origin." (PMID 38892169, 2024). "Tuberous sclerosis is another AD “tumor syndrome,” caused by pathogenic variants in the TSC1 or TSC2 tumor suppressor genes, tuberin and hamartin, that inhibit the mammalian target of rapamycin (mTOR) pathway." (PMID 37644229, 2024). "Tuberous Sclerosis Complex (TSC) is caused by loss of function germline variants in the TSC1 or TSC2 tumor suppressor genes." (PMID 38373162, 2024).
tumor (continued). "An inactivating mutation of the tumor suppressor genes, TSC1 or TSC2, leads to the mammalian target of rapamycin complex 1 (mTORC1) activation causing increased cell growth, making rapamycin and its analogs (like sirolimus) valuable treatment options for LAM." (PMID 39156285, 2024). "This study reported that the inactivation of Tsc1 results in the augmentation of both the frequency and size of tumors, suggesting that Tsc1 functions as a potent tumor-suppressor gene linked to the PI3K/AKT/mTOR pathway in SCLC." (PMID 38473324, 2024). "Like other tumor suppressors, there are multiple classes of pathogenic mutations found in both TSC1 and TSC2 that contribute to disease." (PMID 39352796, 2024). "Barcoding of SCLC tumor clones referring to a panel of 40 candidate genes revealed that Tsc1 and Pten inactivation resulted in increased tumor size, while Pcna/Arid1a alterations were associated with decreased TMB." (PMID 38395864, 2024). "Loss of NF1, TSC1, or TβRII induced tumor cell-autonomous inflammatory reprogramming through alterations in chromatin accessibility and elevated IL6-JAK signaling." (PMID 38997291, 2024). "Peli1 enhances the stability of the tuberous sclerosis 1 (TSC1)/TSC2 complex in tumor-infiltrating CD8+ T cells by mediating K63-linked TSC1 ubiquitination." (PMID 38179042, 2023). "Two bi-steric mTORC1 inhibitors (RMC-4627 and RMC-6272) were assessed on multiple tumor cell lines with mTORC1 hyperactivation secondary to TSC1 or TSC2 loss." (PMID 37909334, 2023). "Tuberous sclerosis complex (TSC) is a rare genetic multisystem disorder caused by loss-of-function mutations in the tumour suppressors TSC1/TSC2, both of which are negative regulators of the mammalian target of rapamycin (mTOR) kinase." (PMID 37108467, 2023). "Of the two patients with response, one had upper tract urothelial carcinoma with biallelic inactivation of TSC1 and high tumor mutational burden." (PMID 35406567, 2022). "Causative genetic mutations of TSC include alterations in tumor-suppressor genes TSC1 or TSC2, which form a complex with TBC1D7 to inhibit mTOR complex 1 (mTORC1), a regulator of cell proliferation and metabolism." (PMID 34982276, 2022). "Subsequent genetic analysis of that patient’s tumor genome identified a TSC1-inactivating mutation as well as a mutation in neurofibromatosis type 2 (NF2)." (PMID 35406567, 2022). "Meanwhile, an ROS scavenger attenuated the hyperactivation of the mTOR pathway in Tsc1 insufficient and Kras-mutated tumor cells." (PMID 36451866, 2022). "Collectively, TSC1/TSC2 loss defines a distinct subtype of NSCLC characterized as inflamed tumor microenvironment and superior sensitivity to ICB." (PMID 35119931, 2022). "Tuberous sclerosis complex (TSC), a congenital syndrome characterized by the widespread development of benign tumors in multiple organs, is caused by heterozygous mutations in one of the tumor-suppressor genes (TSC1 or TSC2)." (PMID 36142719, 2022). "Mutations in one of the tumor suppressor genes, TSC1 or TSC2, lead to an aberrant hyperactivation of the mammalian TOR pathway." (PMID 35639710, 2022). "TSC1/TSC2 loss defines a distinct subtype of NSCLC with inflamed tumor microenvironment and superior sensitivity to ICB therapy." (PMID 35119931, 2022). "Mutation in one of the two tumor suppressor genes, TSC1 encoding hamartin, and TSC2 encoding tuberin is accountable for approximately 85% of cases of this multisystemic tumor syndrome called TSC." (PMID 35600170, 2022). "Tuberous sclerosis complex 1 (TSC1) is a tumor suppressor that promotes the inhibition of mechanistic target of rapamycin (mTOR) pathway, and mutations in TSC1 lead to a rare complex disorder of the same name." (PMID 35645731, 2022). "Approximately 50% of HCC tumors exhibit loss of the tumor suppressors Pten, Tsc1, or Tsc2 leading to aberrant PI3K–AKT–mTOR signaling." (PMID 34348664, 2021).
tumor (continued). "Tuberous sclerosis complex (TSC) is a multisystem neurocutaneous genetic disorder caused by mutations in the tumor suppressor genes TSC1 and TSC2, located on chromosomes 9 and 16, respectively." (PMID 34744957, 2021). "In the patient without VHL mutation, we found alterations in CUL3, DOT1L, SETD2 and TSC1 in the primary tumor, with the addition of BAP1 gene mutation in its analyzable PMs." (PMID 34885018, 2021). "We observed overexpression of GD3 in LAM, wherein mutations in TSC1 or TSC2 are responsible for tumor development." (PMID 34806651, 2021). "In the recent years, efforts have been made to elucidate TSC phenotypic variability, to comprehend the large spectrum of TSC1/2 mutations, and to clarify the mechanisms of tumor formation by focusing on mTORC1 and its related pathways." (PMID 34609442, 2021). "Instead of becoming cytostatic, Rapamycin treatment increased apoptosis in TSC1-deficient tumors and the Rapamycin-treated tumor cells were spindle-shape with round or oval nuclei." (PMID 33923449, 2021). "Cancer evolves via a multistep process and molecular events in addition to TSC1 deficiency during tumor development." (PMID 32363190, 2020). "Previously, tumor developed by TSC1 deficiency has been considered as benign with a high rate of apoptosis." (PMID 32363190, 2020). "The absence of pathogenic genomic alterations in the exons of 160 tumour-related genes upon next-generation sequencing further corroborates the finding that this TSC1 intronic branch point mutation is the cause of the MMPH." (PMID 30794603, 2019). "The tumour suppressor genes TSC1 and TSC2, respectively, encode hamartin and tuberin, which are involved in direct control of the activity of mechanistic target of rapamycin complex 1 (mTORC1)." (PMID 31088250, 2019). "Loss of function mutations of the tumour suppressor TSC1 are seen in bladder cancer, while 25 different TSC2 mutation sites, mainly in or near the RAP-GAP domain, have been reported in pancreatic neuroendocrine tumours (PNET)." (PMID 35582282, 2019). "There is some evidence that tumours with mutations in MTOR/TSC1/2 have a better response to rapalogs, although statistical significance has not been reached." (PMID 30099580, 2018). "These tumors are characteristically driven by deleterious mutations in the tumor suppressors TSC1 and TSC2, whose gene products typically act to inhibit mTOR." (PMID 30285856, 2018). "Mutations in the tumour suppressor genes TSC1 and TSC2 are well-described activating mutations in the kinase domain of the mTOR pathway." (PMID 30220708, 2018). "Molecular analysis of the AML and adjacent normal kidney tissue from this patient demonstrates that this tumor is a sporadic renal AML caused by somatic loss of Tsc1/2 protein." (PMID 29774133, 2018). "We attempted to sequence the normal kidney and tumor tissue to identify possible somatic mutations in TSC1 or TSC2; however, unfortunately we were unable to obtain high quality sequence information." (PMID 29774133, 2018). "We further demonstrate that FNIP1 and Tsc1 are capable of compensating for each other in the chaperoning of mutated FLCN tumor suppressor." (PMID 29774133, 2018). "Taken together, our data suggests that this tumor is a sporadic renal AML as a result of somatic loss of Tsc1/2 in the setting of BHD syndrome." (PMID 29774133, 2018). "Limited molecular studies have demonstrated recurring copy number alterations and TSC1 or TSC2 mutations in the sporadic tumours." (PMID 30123932, 2018). "The patient’s tumor tissue was assayed by comprehensive genomic profiling which revealed presence of a TSC1 partial loss." (PMID 28302097, 2017).
tumor (continued). "Four tumor samples showed copy number loss or a mutation of TSC1 and one tumor showed loss of TSC2; these events were evenly divided over responders and non-responders." (PMID 28903445, 2017). "TSC1 is a tumor suppressor gene whose mutation leads to the tuberous sclerosis complex syndrome, a genetic disorder that causes benign tumors in skin, brain and other organs." (PMID 29292732, 2017). "TSC1/TSC2 mutation analysis was performed as part of routine clinical care on blood or tumor DNA for 19 subjects, such that 7 had TSC1 and 12 had TSC2 mutations." (PMID 29221145, 2017). "This disorder is caused by inactivating mutations in either of two tumor suppressor genes: TSC1 or TSC2." (PMID 27078846, 2016). "Tuberous Sclerosis Complex (TSC) is a multi-system genetic disease caused by autosomal dominant mutations in the tumor suppressor genes encoding hamartin (TSC1) or tuberin (TSC2)." (PMID 26892894, 2016). "This is an autosomal dominant phacomatosis, due, in 60 % of cases, to spontaneous mutation in two tumor suppressor genes (TSC1 and TSC2)." (PMID 26861567, 2016). "Haematopoietic-specific deletion of Tsc1 causes a marked decrease in the number of NK cells and compromises rejection of ‘missing-self' haematopoietic tumours and allogeneic bone marrow." (PMID 27601261, 2016). "DNA sequencing of his tumor revealed the presence of a tuberous sclerosis 1 (TSC1) mutation, so daily everolimus, which inhibits mammalian target of rapamycin, was started." (PMID 26500758, 2015). "Expression of tuberous sclerosis complex (TSC) 1/hamartin, a protein encoded by the TSC1 gene, was reduced in the tumor in comparison to the surrounding liver tissue." (PMID 26943379, 2015). "Some of the top candidates include MLL3 (8 out of 11 tumor samples) and TSC1 (6 out of 11) which are previously reported to be mutated in human carcinomas." (PMID 26305677, 2015). "In fact, clinical tumor samples demonstrating a loss of functional TSC1/TSC2 also showed loss of mTORC2 function." (PMID 25283550, 2014). "In the genetic disease TSC, which is caused by mutations in Tsc1 or Tsc2, patients develop benign tumours in multiple organs including the brain." (PMID 25210733, 2014). "In tumor samples, loss of TSC1/TSC2 function resulted in subsequent loss of mTORC2 activity and mTORC1 hyperactivation." (PMID 25283550, 2014). "Tsc1 and Tsc2 are two tumor suppressor genes, inactivating mutations in either of which explains genetically why patients suffer multiple tumors in various tissues and organs." (PMID 23335988, 2013). "The present finding of consistent overexpression of p-S6 protein in a rare rat mammary angiosarcoma associated with OTA exposure, suggests that genetic changes targeted by OTA also caused this tumour, potentially via change in the Tsc1 gene." (PMID 23105973, 2012). "Supporting this view, mutations in TSC1/2 result in Tuberous Sclerosis Complex, a rare autosomal dominant disease that is characterized by widespread benign tumor formation." (PMID 23144631, 2012). "TSC1 is another critical tumor suppressor, implicated downstream in the PI3K/AKT and RAS/ERK pathways." (PMID 22613809, 2011). "Loss of heterozygosity was studied using matched blood and tumor DNA samples and microsatellite markers from the TSC1, TSC2 and PTEN candidate regions." (PMID 18538015, 2008). "Based on these observations, we hypothesized that TSC1 deficiency promotes tumor immune evasion in CRC through mTORC1-mediated dysregulation of PD-L1 sialylation." (PMID 41445741, 2025). "Cytokines such as IL-4 and IL-13 within the tumor microenvironment regulate the polarization of tumor-associated macrophages (TAMs) through downstream Stat6-dependent inhibition of Arg1, activation of PPARγ, and TSC1-mediated inhibition of mTOR." (PMID 39676873, 2024).